AIFM3 (AIF family member 3)
Description:
Induces apoptosis through a caspase dependent pathway. Reduces mitochondrial membrane potential.
Synonyms: AIFL; FLJ30473
Tractability: Small molecule: a structure with a bound ligand is known.
Gene: Protein-coding gene on chromosome 22 (20,965,108 to 20,981,364, forward strand). Ensembl gene ENSG00000183773.
Subcellular location: Mitochondrion
Subcellular location (Human Protein Atlas): Mitochondria
Gene Ontology:
Molecular function: 2 iron, 2 sulfur cluster binding; oxidoreductase activity
Biological process: execution phase of apoptosis
Cellular component: endoplasmic reticulum; mitochondrial inner membrane; mitochondrion; nucleus
Genetic constraint (gnomAD): Loss-of-function variants: 71 observed, 77.97 expected, observed/expected ratio (o/e) 0.91, 90% interval 0.75 to 1.11. The upper end of that interval is the gene's LOEUF score, 1.11, which puts it in group 4 of 6, group 1 being the genes least tolerant of losing a copy. Missense variants: 748 observed, 805.02 expected, observed/expected ratio (o/e) 0.93, 90% interval 0.87 to 0.99. Synonymous variants: 337 observed, 323.93 expected, observed/expected ratio (o/e) 1.04, 90% interval 0.95 to 1.14.
Homologues: Orthologues: chimpanzee AIFM3 (99% identical), guinea pig AIFM3 (97% identical), chimpanzee AIFM3 (97% identical), mouse Aifm3 (96% identical), pig AIFM3 (96% identical), rat Aifm3 (96% identical), macaque AIFM3 (83% identical), tropical clawed frog aifm3 (77% identical), zebrafish aifm3 (66% identical), rabbit AIFM3 (56% identical), Drosophila melanogaster CG4199 (36% identical), Drosophila melanogaster CG10700 (33% identical), and 1 more. Paralogues in human: TXNRD3 (20% identical), TXNRD1 (19% identical), AIFM1 (17% identical), TXNRD2 (17% identical), GSR (16% identical), DLD (16% identical), PYROXD1 (13% identical).
Diseases named in the same sentence as AIFM3 in open-access papers:
AIFM3 is named in the same sentence as 23 diseases in open-access papers, as found by Europe PMC text mining. Sharing a sentence is not in itself a finding about the gene and the disease. The quoted sentences say what the papers report.
breast carcinoma (8 papers, 2019 to 2025). "Recently, AIFM3 was found to be overexpressed in breast cancer patients and was significantly associated with tumor size, lymph node metastases, TNM staging, and a shorter overall survival and disease-free survival." (PMID 33435319, 2021). "AIFM3 was observed to be highly expressed in breast cancer tissues and associated with shorter overall survival and disease-free survival." (PMID 31827401, 2019). "AIFM3 is a direct target of miR-210 and is associated with the proliferation of human liver cancer cells, and overexpression of AIFM3 predicts stronger proliferative and invasive behavior in breast cancer." (PMID 34512722, 2021). "Related to this, the AIFM3 gene is located on chromosome 22q11, a small segment of chromosome 22 which has been implicated in contributing to metastasis and progression of colorectal cancer, breast cancer, and prostate cancer." (PMID 32664187, 2020). "Besides, in this study, high serum AIFM3 level was associated with lymph node metastasis which was similar to the recent report in breast cancer tissues." (PMID 32664187, 2020). "However, apoptosis usually presents two-sideness in regulating the life-death balance: higher Aifm3 levels are found associated with shorter overall survival in breast cancer, while Aifm3 also decreases stem-like properties of breast cancer stem cells and has potential to suppress tumor progression." (PMID 38164361, 2024). "Recently, apoptosis-related protein AIFM3 was found to be increased in breast cancer and cholangiocarcinoma." (PMID 39857952, 2025). "The concordant findings of high expression of AIFM3 in tumor tissue and poor OS have also been reported in breast cancer." (PMID 32664187, 2020). "To further elucidate how AIFM3 was involved in the breast cancer development, we analyzed the correlation of AIFM3 expression with clinical pathology factors." (PMID 31088422, 2019). "To elucidate whether AIFM3 contributed to breast cancer, we evaluated the expression levels of AIFM3 by IHC in 151 real samples." (PMID 31088422, 2019). "To evaluate whether AIFM3 expression could serve as a predictive marker for breast cancer, we used ROC (receiver operating characteristic curve) analysis." (PMID 31088422, 2019). "AIFM3 was significantly more expressed in breast cancer tissues than in normal tissues." (PMID 31088422, 2019). "Firstly, AIFM3 is more expressed in breast cancer tissue than in normal tissues." (PMID 31088422, 2019). "AIFM3 might exert late and early response to estrogen and decrease stem-like properties of breast cancer cells and stemness of breast cancer stem cells." (PMID 31088422, 2019). "AIFM3 might be closely related to occurrence and development of breast cancer." (PMID 31088422, 2019). "The key findings involve a significant reduction in AIFM3-positive cells in the lamina propria, especially in advanced CRC stages (Dukes B–D), contrasting with increased AIFM3 levels in breast cancer and cholangiocarcinoma." (PMID 39857952, 2025). "In the present study, we used bioinformatics analysis including the Cancer Genome Atlas-breast cancer (TCGA-BRCA), Kaplan-Meier survival analysis and Gene Set Enrichment Analysis (GSEA) to demonstrate expression level, survival and the mechanisms related to AIFM3 signature in BC." (PMID 31088422, 2019). "The TCGA RNA Seq data demonstrated that AIFM3 was significantly over-expressed in breast cancer compared with non-cancerous tissue samples." (PMID 31088422, 2019).
hepatoma (6 papers, 2013 to 2021). "miR-210 increased radioresistance of hypoxic hepatoma cells by targeting apoptosis-inducing factor mitochondria-associated 3 (AIFM3)." (PMID 32585857, 2020). "Downregulation of miR-210 promoted and AIFM3 inhibition attenuated IR-induced apoptosis in hypoxic hepatoma cells." (PMID 32585857, 2020). "AIFM3 is a direct target of miR-210 which is related to proliferation and enhanced radio-sensitivity in hypoxic human hepatoma cells." (PMID 31088422, 2019). "To investigate the mechanism underlying the knockdown of miR-210 mediated growth delay in SMMC-7721/Lv-anti-210 xenograft, we analyzed protein expression of HIF-1α, MNT, EFNA3 and AIFM3 genes in human hepatoma xenograft by Western blot." (PMID 23618526, 2013). "To investigate the mechanism underlying the knockdown of miR-210 mediated tumor growth delay, we analyzed protein expression of HIF-1α gene and miR-210 targeted MNT, EFNA3 and AIFM3 genes in human hepatoma xenograft by Western blot." (PMID 23618526, 2013). "The Western blot results indicated that knockdown of miR-210 decreased HIF-1α protein and increased protein expression of MNT, EFNA3 and AIFM3 genes in human hepatoma xenograft." (PMID 23618526, 2013). "It has been suggested that AIFM3 expression is a direct target of miR-210, whereas the down-regulation of miR-210 and the increased expression of AIFM3 inhibits proliferation, induces apoptosis and enhances radiosensitivity in hypoxic human hepatoma cells in vitro." (PMID 33435319, 2021). "AIFM3 was a direct target of miR-210 which was related to proliferation of human hepatoma cells." (PMID 31088422, 2019). "AIFM3, a gene homologous to the apoptosis-inducing factor (AIF), is a direct target of miR-210 in human hepatoma cells." (PMID 23618526, 2013).
cholangiocarcinoma (4 papers, 2019 to 2025). A carcinoma that arises from the intrahepatic biliary tree (intrahepatic cholangiocarcinoma) or from the junction, or adjacent to the junction, of the right and left hepatic ducts (hilar cholangiocarcinoma). "AIFM3 is aberrantly expressed only in cholangiocarcinoma (CCA) tissues, suggesting that AIFM3 can be a potential target molecule for CCA chemotherapy." (PMID 31088422, 2019). "Instead, the overexpression of AIFM3 was found in the mitochondria of cholangiocarcinoma tissues, but not in the adjacent non-cancerous tissues." (PMID 33435319, 2021).
colorectal cancer (2 papers, 2020 to 2025). A primary or metastatic malignant neoplasm that affects the colon or rectum. "The expression of AIFM3, WNT4, and VGLL4 in relation to microsatellite instability (MSI) status in colorectal cancer was analyzed using a cohort of 108 patients extracted from the TCGA colon and rectal cancer (COADREAD) study in the XENA database." (PMID 39857952, 2025). "This study provides novel findings highlighting the expression levels of three important apoptotic and growth signaling proteins, AIFM3, VGLL4, and WNT4, involved in different clinically relevant stages of progression in patients with colorectal cancer (CRC)." (PMID 39857952, 2025). "Furthermore, AIFM3 showed a statistically significant difference in expression between MSI-stable and MSI-unstable colorectal cancer, highlighting its potential as a biomarker for MSI status." (PMID 39857952, 2025). "Therefore, this study highlights the clinical potential of AIFM3, VGLL4, and WNT4 in colorectal cancer (CRC) progression." (PMID 39857952, 2025). "Notably, AIFM3 exhibited a statistically significant difference in expression levels between the MSI-stable and MSI-unstable groups, suggesting its potential utility as a biomarker for MSI in colorectal cancer." (PMID 39857952, 2025).
glioma (2 papers, 2021). A benign or malignant brain and spinal cord tumor that arises from glial cells (astrocytes, oligodendrocytes, ependymal cells). "Importantly, previous studies reported that AIFM3, LDHD, LYNX1, SCN2B or TMEM56 were all negatively corelated with glioma, and GINS1, KIFC1, NUF2, NUSAP1 or TPX2 were both positively related to glioma progression." (PMID 33277782, 2021).
lymph node metastasis (2 papers, 2019 to 2020). "The results demonstrated that serum AIFM3 level was associated with lymph node metastasis, age, and survival time (p = 0.001, p = 0.002, and p = 0.017, respectively), but not with other parameters." (PMID 32664187, 2020). "There was a significant association of AIFM3 expression with tumor size, lymph node metastasis, molecular typing and TNM staging." (PMID 31088422, 2019). "AIFM3 expression was associated with tumor size, lymph node metastasis, TNM stage and molecular typing." (PMID 31088422, 2019). "In the present study, higher serum AIFM3 level was associated with lymph node metastasis and poor overall survival of the patients, so that serum AIFM3 level could be used as a prognostic marker for CCA patients." (PMID 32664187, 2020). "There is a significant association of AIFM3 expression with tumor size, lymph node metastasis, TNM staging and other clinical pathology factors, indicating that AIFM3 may be related to the occurrence and development of BC." (PMID 31088422, 2019). "When correlation between serum AIFM3 levels and the clinicopathological parameters of CCA patients were examined, serum AIFM3 levels correlated significantly with lymph node metastasis, age, and the patients’ overall survival (OS)." (PMID 32664187, 2020). "Multivariate analysis showed that lymph node metastasis (P = 0.015) and TNM stage (P = 0.009/0.003) were independent factors of AIFM3 expression." (PMID 31088422, 2019). "Lymph node metastasis and TNM stage were independent factors of AIFM3 expression." (PMID 31088422, 2019).
bladder cancer (1 paper, 2020). "On the other hand, higher expression of AIFM3 mRNA dataset is correlated with greater patients’ survival time in bladder cancer tissues." (PMID 32664187, 2020).
cerebral infarct (1 paper, 2012). "CASP3 was augmented 24 h after stroke in the core of the lesion, whereas CASP9 and AIFM3 levels were decreased after cerebral infarct in both core and PI areas, but these differences with normal levels were not significant in the PI area 3 d after the lesion." (PMID 23284893, 2012).
renal failure (1 paper, 2021). "The gene AIFM3 at 22q11.2 was associated with renal failure." (PMID 34715901, 2021).
Sleep apnea (1 paper, 2017). An intermittent cessation of airflow at the mouth and nose during sleep is known as sleep apnea. "Significant associations of symptoms of sleep apnea were observed with six rare variants [minor allele frequency (MAF) <1%] (located in ACE, AIFM3, LIPJ, MUC2, AP2A2, SH3BP1)." (PMID 29093733, 2017).
tumor (11 papers, 2013 to 2025). "AIFM3 expression had a significant association with tumor size, lymph node metastasis, TNM stage and molecular typing." (PMID 31088422, 2019). "Conversely, genes involved in cell death (Aifm3, FC = –1.9, P = 0.04) or tumor suppression (SerpinB2, FC = –35.0, P = 7 × 10–4; Arhgap15, FC = –3.6, P = 0.03; Frk, FC = –1.7, P = 0.01) were downregulated." (PMID 36892943, 2023). "The results showed that serum AIFM3 levels were significantly decreased in all 4 cases after surgical removal of tumor mass." (PMID 32664187, 2020). "Since the high serum AIFM3 level is associated with the poor prognosis and lymph node metastasis of the patients with CCA, the role of AIFM3 in tumor invasion/metastasis as well as tumor proliferation requires examination in the future." (PMID 32664187, 2020). "Univariate analysis illustrated the significant correlation between AIFM3 expression and tumor size (P = 0.013), lymph node metastasis (P = 0.001), molecular typing (P = 0.031) and TNM stage (P < 0.001)." (PMID 31088422, 2019). "We next tested whether there is an association between a higher AIFM3 and DLK1 copy number state and age of onset, gender, tumor size, multifocality, extrathyroidal extension, vascular invasion and AJCC staging system." (PMID 33435319, 2021). "AIFM3 was relevant to oxidative phosphorylation, which indicated AIFM3 might participate in maintaining the energy metabolism of tumor cells." (PMID 31088422, 2019). "AIFM3 may have the potential to suppress tumor via targeting BCSCs." (PMID 31088422, 2019). "Gene expression of AIFM3 (p < 0.0001), VGLL4 (p < 0.0001), and WNT4 (p < 0.01) was significantly altered in tumor tissues in comparison to the control tissues." (PMID 39857952, 2025). "The results indicated that AIFM3, HSH2D, and PTPN6 were significantly up-regulated, while DCHS1, PTGIS, FLRT2, PCSK5, and CLSTN2 were significantly down-regulated in tumor samples compared with normal samples." (PMID 34512722, 2021). "AIFM3 correlated to DNA repair and peroxisome, which indicated AIFM3 might participated in reactive oxygen species pathway to regulate cancer development.These results provides new insights for understanding the molecular mechanism of AIFM3 in regulating malignant tumor biology process." (PMID 31088422, 2019). "Interestingly, when a tumor sample showed a negative or weak staining for AIFM3, it also showed a similar pattern for DLK1 (p < 0.02)." (PMID 33435319, 2021).
cancer (9 papers, 2013 to 2025). A tumor composed of atypical neoplastic, often pleomorphic cells that invade other tissues. "Apoptosis-inducing factor, mitochondrion-associated 3 (AIFM3) is highly expressed in several cancers including CCA." (PMID 32664187, 2020). "Furthermore, the protein–protein interaction networks revealed that AIFM3 molecule linked to mitochondrial carcinogenesis-related proteins and various key molecules in cancer progression." (PMID 32664187, 2020). "Although AIFM3 is widely expressed in many tissues, the physiological role of AIFM3 or its role in cancer has rarely been reported." (PMID 32664187, 2020). "Serum AIFM3 level should be further investigated in closely related diseases and other cancer patients in order to discriminate other diseases." (PMID 32664187, 2020). "Although higher expression of AIFM3 was observed in some cancers, this study firstly reported that serum AIFM3 level can be a prognostic marker of CCA." (PMID 32664187, 2020). "Although AIFM3 is widely expressed in various tissues, the function of AIFM3 in occurrence and development progress of cancer is rarely reported." (PMID 31088422, 2019). "Apoptosis-Inducing Factor Mitochondrion-associated 3 (AIFM3) is widely expressed in various tissues and aberrantly expressed in several cancers." (PMID 31088422, 2019). "miR-210, miR-17-92, miR-31, miR-221 and miR-222 have been documented to be down-regulated in radioresistant cancer cells, to regulate the expression of AIFM3, MNT and PTEN respectively, and to promote cancer radioresistance." (PMID 24283459, 2013). "AIFM3 appears in healthy tissue and early cancer stages but disappears as the cancer worsens." (PMID 39857952, 2025). "Apoptotic inducing factor M3 (AIFM3), a mitochondrial protein involved in the execution phase of apoptosis, is widely expressed across multiple tissues and shows abnormal expression in various cancers." (PMID 39857952, 2025). "AIFM3 express in a variety of tissues and aberrantly expressed in several cancers, widely." (PMID 34512722, 2021). "The studies of AIFM3 in cancer are limited to several cancers." (PMID 31088422, 2019). "Thus, AIFM3 might be a potential biomarker for some cancers." (PMID 32664187, 2020).
AIFM3 also shares sentences with these, for which no sentence is quoted: disorders of iris (1 paper); liver cancer (1); Medullary Thyroid Carcinomas (1); mood disorder (1); osteoporosis (1); ovarian carcinoma (1); prostate carcinoma (1); psychosis (1); rectal cancer (1); schizophrenia (1); Stroke (1).